ANXA4 (annexin A4)
Diseases named in the same sentence as ANXA4 in open-access papers (continued):
Sharing a sentence is not in itself a finding about the gene and the disease.
tumor (40 papers, 2005 to 2025). "The results of this study showed that the p65 subunit was required for the feedback circuit between ANXA4 and NF-κB, which has been implicated in tumor development and progress." (PMID 27491820, 2016). "Increased expression of ANXA4 is associated with increased tumor stage and poorer patient prognosis in colorectal cancer, and with chemoresistance and poorer patient prognosis in ovarian SC." (PMID 24244679, 2013). "Annexin A4 had a distinct subcellular localisation in tumour cells and this was linked to loss of cell-to-cell adhesion and increased tumour cell dissemination." (PMID 18071363, 2008). "Annexin A4 (ANXA4) is a protein that binds to Ca2+ and phospholipids, and it is part of the Annexin family, which plays a role in the development of various tumor types through NF-κB signaling." (PMID 39796643, 2024). "Previous studies have shown that ANXA4 modulates membrane permeability and membrane trafficking, participates in cellular growth and apoptosis, and enhances tumor invasion." (PMID 39399103, 2024). "ANXA4 can regulate membrane permeability and membrane transport, participate in cell growth and apoptosis, increase tumor invasion and promote antitumor drug resistance." (PMID 39399103, 2024). "Previous studies suggest that ANXA4 enhances tumor invasion and promotes anti-tumor drug resistance." (PMID 35681609, 2022). "Then ANXA4 expression levels between tumor and normal tissues were analyzed using data from the TCGA database." (PMID 34540918, 2021). "The in vivo xenograft model indicated that the ANXA4 overexpression groups had significantly higher tumourigenicity with obvious haemorrhagic necrosis on the tumour surface than the control group (n=6, n1=3/6 VS n2=0/6)." (PMID 33761465, 2021). "Blocking AnxA4 translocation with a heptapeptide derived from the tumour suppressor FHIT restored the chemosensitivity to paclitaxel." (PMID 33810523, 2021). "It is conceivable that ANXA4 is highly expressed in multiple tumour types and is an indicator for tumour development, invasion, chemo- resistance, and poor outcomes in cancer patients." (PMID 33761465, 2021). "ANXA4 expression was higher in the CRC tissue samples than in the tumour-adjacent tissue samples and was detected in both the plasma membrane and cytosolic fractions in the CRC tissue samples, whereas ANXA4 expression was minimal in the normal tissue samples." (PMID 33761465, 2021). "Higher expression of ANXA4 was correlated with tumour differentiation (p<0.001) and metastasis (p<0.05), but it was not correlated with sex, age, tumour location or tumour size." (PMID 33761465, 2021). "The most three tumor types relevant to ANXA4 expression levels were DLBC, GBM, and UCS (immune score), DLBC, GBM, and UCS (estimate score), TGCT, GBM, and THYM (stromal score)." (PMID 34540918, 2021). "The same results were obtained in the context of ANXA4 overexpression in the subcutaneously transplanted tumour nude mouse model." (PMID 33761465, 2021). "One reason is that upregulated expression of ANXA4 promotes tumour cell growth, migration, and invasion by activating NF-κB pathway." (PMID 30404616, 2018). "The modifications of ANXA4 by Lewis y antigen affect the binding of ANXA4 and NF-KB p50, and promote tumor progression of OCCC, resulting in a poor prognosis." (PMID 29296226, 2017). "So, in OCCC, does the observation that both ANXA4 and NF-kB p50 promote tumor progression have anything to do with their modifications?" (PMID 29296226, 2017). "Currently, the effects of ANXA4 glycosylation modification are unclear, as are its roles in the process of tumor occurrence and development that involve ANXA4." (PMID 29296226, 2017).
tumor (continued). "Taken together, these data indicate that up-regulation of ANXA4 leads to activation of the NF-κB pathway and its target genes in a feedback regulatory mechanism via the p65 subunit, resulting in tumor growth in GBC." (PMID 27491820, 2016). "These NF-κB downstream target genes were down-regulated in tumors from mice injected with ANXA4-knockdown clones, indicating that NF-κB plays an important role in tumor growth regulated by ANXA4 in GBC." (PMID 27491820, 2016). "In vivo, ANXA4 knockdown inhibited tumor growth of GBC cells in nude mice and down-regulated the expression of downstream factors in the NF-κB signaling pathway." (PMID 27491820, 2016). "In renal cell carcinoma, up-regulation of ANXA4 is involved in dissemination of tumor cells, promoting cell migration." (PMID 22970268, 2012). "The highest percentage of strong staining was seen in annexin A4, with 64.9% of tumours showing strong staining." (PMID 18071363, 2008). "As in normal and primary tumours, annexin A4 showed the greatest percentage of strong staining at 62.3% of tumours." (PMID 18071363, 2008). "Additionally, it has been demonstrated that overexpressed annexin A4 promotes cell migration in a model tumour system, which correlates with our observation that annexin A4 expression increased as tumour stage progressed, such findings are indicative that annexin A4 is implicated in tumour spread." (PMID 18071363, 2008). "This study suggests that ANXA4 acts as a tumour suppressor gene." (PMID 39290334, 2022). "Likewise, AnxA4 depletion decelerated the in vivo growth of tumours derived from basal-like breast cancer cell lines." (PMID 33810523, 2021). "Annexin A4 (ANXA4) can reversibly bind to membrane phospholipids in a calcium-dependent manner and is involved in regulating tumour cell proliferation, apoptosis, adhesion, invasion, metastasis, and chemotherapy resistance, as well as other biological processes." (PMID 33761465, 2021). "ANXA4 accelerates membrane repair, upregulates exocytosis, decreases mobility and is involved in skin wound haemostasis, human heart failure and tumours." (PMID 33761465, 2021). "ANXA4 might influence the efficacy of immunotherapy via tumor burden and microsatellite instability." (PMID 34540918, 2021). "In addition, HT-29 cells transfected with ANXA4-overexpression or empty vectors were injected subcutaneously into nude mice, and tumour volume was evaluated at 7, 12, 18, and 25 days." (PMID 33761465, 2021). "Recent studies have shown that, ANXA4 can reversibly bind to membrane phospholipids in a calcium-dependent manner, and is involved in regulating tumor cell proliferation, apoptosis, adhesion, invasion, metastasis, and chemotherapy resistance, as well as other biological processes." (PMID 29296226, 2017). "Tumor volume and weight were significantly decreased in mice injected with ANXA4-knockdown cells." (PMID 27491820, 2016). "Up-regulation of ANXA4 is specifically found in H. pylori-infected tumor tissues." (PMID 22970268, 2012). "Furthermore, CRC patient tumour tissue samples, tumour-adjacent tissue samples and normal colon tissue samples (n=20) were used to examine the protein level and subcellular distribution of ANXA4 by western blotting of membrane-cytoplasm fractionated lysates." (PMID 33761465, 2021). "For example, SUMO modification of annexin A4 (ANXA4), a calcium-binding protein located in the gastrointestinal tract, increases its expression and promotes epithelial-mesenchymal transition (EMT) of tumor cells." (PMID 37777749, 2023). "Annexin A4 (ANXA4) is a Ca2+- and phospholipid-binding protein that belongs to the annexin family, which is involved in the development of multiple tumour types via NF-κB signalling." (PMID 33761465, 2021). "The expression levels of ANXA2, ANXA3, ANXA4, ANXA8, and ANXA9 were significantly increased in tumor tissues compared with normal tissues." (PMID 34484309, 2021).
tumor (continued). "IHC identified the protein expression levels of ANXA4 and the EMT signalling pathway factors E-cadherin, Vimentin and Snail in tumours." (PMID 33761465, 2021). "To test whether we could distinguish the two ANXA4 subtypes in clinical samples as we did in established cell lines, we used nine samples from patients with CCC from whom frozen tumor tissues of their primary surgeries were available." (PMID 24244679, 2013). "However, some proteins we found differed from previously identified proteins (Such as ANXA4, CFHR2, CHP, CTSB and so on), which may result from ethnic differences or tumor heterogeneity." (PMID 24139065, 2013). "In our research, we proved for the first time that ANXA4 mRNA expression was higher in KIRC tissues than in normal tissues, but this expression did not correlate with tumour progression stage." (PMID 39290334, 2022). "Immunohistochemical staining revealed that ANXA4 protein was abundantly present in human GBC tumors, compared with weak or no expression in normal tumor-adjacent tissues." (PMID 27491820, 2016).
infection (4 papers, 2013 to 2022). The state of being infected such as from the introduction of a foreign agent such as serum, vaccine, antigenic substance or organism. "Notably, several members from Annexin A family (ANXA1, ANXA2, ANXA4, ANXA5 and ANXA6) were overrepresented in DEVs from Lm-infected BMDCs but remained unaltered in total cell lysates, suggesting a specific sorting during infection of these ANXA family members to EVs." (PMID 36131943, 2022).
adenocarcinoma (3 papers, 2016 to 2020). A common cancer characterized by the presence of malignant glandular cells. "ANXA4 knockdown also inhibited cell migration and invasion, in accordance with the reported involvement of this gene in pathogenic proliferation and invasion of adenocarcinoma cells." (PMID 27491820, 2016).
ANXA4 also shares sentences with these, for which no sentence is quoted: renal carcinoma (3 papers); autoimmune conditions (2); prostate carcinoma (2); Warthin tumor (2); adenosquamous carcinoma (1); Anxiety (1); asthma (1); atrial fibrillation (1); benign tumors of the salivary glands (1); breast tumors (1); cardiovascular disease (1); complement deficiency (1); diabetes (1); endometrioid carcinomas (1); gastritis (1); gonococcal arthritis (1); ischemic stroke (1); kidney tumor (1); laryngeal carcinoma (1); leprosy (1); liposarcoma (1); metastatic colorectal cancer (1); myeloma (1); ovarian clear cell adenocarcinoma (1); ovarian serous adenocarcinoma (1); ovarian tumors (1); pancreatic cancer (1); parasite infection (1); promyelocytic leukemia (1); renal cell carcinoma (1).
A further 4 diseases each share a sentence with ANXA4 in 1 paper.